CAV1 (caveolin 1)
Diseases named in the same sentence as CAV1 in open-access papers (continued):
Sharing a sentence is not in itself a finding about the gene and the disease.
glioma (continued). "We also found that Cav-1 expression and VM formation were significantly upregulated in HGG compared with LGG, and both of them were significantly correlated with shortened survival of glioma patients, suggesting Cav-1 or VM formation as a prognostic indicator in glioma." (PMID 34287575, 2021). "In conclusion, our study suggests that Cav-1 expression and VM formation may be correlated with each other and both of them could be unfavorable prognostic factors in patients with glioma." (PMID 34287575, 2021). "Since Cav-1 upregulation and VM formation are both correlated with glioma grades and outcomes, we next sought to investigate whether there is a correlation between Cav-1 and VM." (PMID 34287575, 2021). "In this study, we examined the expression of Cav-1 and VM formation in glioma tissues." (PMID 34287575, 2021). "Consequently, Cav-1 knockdown significantly inhibits glioma proliferation and metastasis." (PMID 40243482, 2025). "Similarly, m6A enrichment in LINC01003 enhances glioma cell migration via the CAV1/FAK pathway." (PMID 41390674, 2025). "Although CAV-1 is a vital regulator of tumour progression, its role in glioma remains unclear." (PMID 38298655, 2024). "However, the molecular mechanism and functional effects of CAV-1 in glioma are still elusive." (PMID 38298655, 2024). "Considering promoting cell migration is one of the important functions of CAV1, and the RNA-sequencing data of resistant cells including two glioma cancer cell lines, we propose that the high expression of CAV1 may render the glioma cells OXPHOS inhibition and promotes cancer cell progression." (PMID 37642765, 2023). "However, the function of CAV1 in gliomas hasn’t been explored." (PMID 37642765, 2023). "Therefore, we identified a key gene CAV1 and deciphered its function in glioma progression and prognosis, proposing that CAV1 may be a therapeutic target for gliomas." (PMID 37642765, 2023). "However, the expression pattern of Cav-1 and the relationship between Cav-1 and VM in glioma remain unclear." (PMID 34287575, 2021). "Therefore, the function of Cav-1 in glioma development remains controversial." (PMID 34287575, 2021). "Indeed, VM formation was found positively correlated with Cav-1 expression in glioma tissues, and patients with Cav-1 overexpression and increased VM formation in combination had poorer prognoses than other patients, suggesting a synergistic role of Cav-1 and VM in glioma progression." (PMID 34287575, 2021). "Considering that Cav-1 contributes to VM formation through the PI3K/Akt signaling cascade in uveal melanomas, we hypothesized that there might be an association between Cav-1 and VM in glioma." (PMID 34287575, 2021). "According to time-dependent ROC, the CAV-1 expression level had a relatively good performance in predicting 1-year, 3-year, 5-year OS and DSS in glioma patients." (PMID 38298655, 2024). "In this experiment, we discovered that CAV-1 activates the PI3K/Akt signaling pathway, triggering the process of EMT and promoting glioma progression." (PMID 38298655, 2024). "In summary, our research findings demonstrate that overexpression of CAV-1 activates the PI3K/Akt signaling pathway by mediating upregulation of PAI-1, ultimately promoting glioma metastasis." (PMID 38298655, 2024). "Molecular and functional experiments indicated that CAV-1 upregulates PAI-1 expression, activates the PI3K/Akt signaling pathway, and promotes EMT and angiogenesis in glioma cells." (PMID 38298655, 2024). "Our previous study found that cancer cells’ energy resource and reliance varies a lot, here we found that CAV1 is highly involved in the glycolysis and OXPHOS-inhibition drug resistance, which partially elucidate the working mechanisms of CAV1 in gliomas." (PMID 37642765, 2023). "However, it remains largely unknown whether Cav-1 expression correlates with VM in glioma." (PMID 34287575, 2021).
glioma (continued). "In the present study, Cav-1 expression and VM formation were examined by immunohistochemistry and CD31/PAS double-staining, respectively, in human glioma tissues." (PMID 34287575, 2021). "In glioma cells and pulmonary artery smooth muscle cells, the 5-HT2A receptor co-immunoprecipitates with cav-1, and in cardiomyocytes with cav-3." (PMID 28555112, 2017). "A recent study found that Cav-1 plays a crucial role in the PI3K/Akt-dependent upregulation of plasminogen activator inhibitor-1 (PAI-1), which promotes glioma proliferation and metastasis through an enhanced epithelial–mesenchymal transition (EMT) and angiogenesis." (PMID 40243482, 2025). "Altogether, these findings suggested that ANXA5, STAT1, CD44, CAV1, MAPT, and ANXA2 might play a vital role in the pathogenesis of gliomas." (PMID 40607003, 2025). "Finally, six genes (ANXA5, STAT1, CD44, CAV1, MAPT, and ANXA2) with the highest degree values were selected as the hub genes for glioma by using the cytoHubba plugin for expression level and prognosis analyses." (PMID 40607003, 2025). "The protein-protein interaction (PPI) network analysis showed that ANXA5, STAT1, CD44, CAV1, ANXA2, and MAPT may serve as candidate biomarkers in glioma diagnosis." (PMID 40607003, 2025). "In summary, a systematic bioinformatics analysis of DEGs demonstrated that ANXA5, STAT1, CD44, CAV1, MAPT, and ANXA2 might serve as potential biomarkers and therapeutic targets for glioma." (PMID 40607003, 2025). "Hence, the mechanism of how ANXA5, STAT1, CD44, CAV1, MAPT, and ANXA2 contributed to the gliomas still need further research." (PMID 40607003, 2025). "Generally, these results suggested that ANXA5, STAT1, CD44, CAV1, MAPT, and ANXA2 might play a critical role in the pathogenesis of glioma, suggesting that the hub genes might be a promising biomarker of glioma." (PMID 40607003, 2025). "In summary, our study provided evidence that CAV-1 activates the PI3K/Akt signaling pathway by upregulating PAI-1, thereby promoting the proliferation and metastasis of glioma through enhanced epithelial-mesenchymal transition (EMT) and angiogenesis, and CAV-1 is involved in the immune infiltration." (PMID 38298655, 2024). "Additionally, CAV-1 regulates the epithelial-mesenchymal transition (EMT) and angiogenesis in glioma cells, thus promoting glioma metastasis." (PMID 38298655, 2024). "Interestingly, we identified a new signaling axis, LINC01003/CAV1/FAK, through which LINC01003 regulates focal adhesion in glioma." (PMID 37270527, 2023). "CAV1 also interacts with other proteins to affect glioma cancer progression, it interacts with TRAF4, an E3 ubiquitin ligase, to maintain its deubiquitylation and stability, thus driving glioma stemness and Temozolomide resistance." (PMID 37642765, 2023). "Therefore, we explored the relationship between CAV1 and glioma stemness from RNA sequencing data in TCGA and GTEX, and found that the expression of CAV1 is positively related to the glioma stemness in pan-cancer analysis." (PMID 37642765, 2023). "However, more experiments, like knockdown or inhibition of Akt or HIF-1α in Cav-1-overexpressing glioma cells and protein-protein interactions in hypoxic conditions, need to be done to evaluate the direct role of Akt and HIF-1α in glioma VM formation." (PMID 34287575, 2021). "Cav-1-dependent expression of HIF-1α and Akt may be involved in the promotive role of Cav-1 in glioma cell proliferation and VM formation." (PMID 34287575, 2021). "The presence of Cav-1 or VM was not correlated with age, sex, or tumor diameter in these 94 glioma patients." (PMID 34287575, 2021). "In rat C6 glioma cells, the CB1 receptor co-localized with caveolin-1." (PMID 34099009, 2021). "As α5β1 integrin played a crucial role in the acquisition of proliferative and clonogenic ability of Cav1-depleted glioma cells, its role in the reduction of proliferation and clonogenicity observed in HNSCC cells with reduced expression of Cav1 was determined." (PMID 26474461, 2015).
glioma (continued). "However, Caveolin-1 is highly represented in gliomas and has an unambiguous negative correlation with patient survival." (PMID 39598347, 2024). "However, till now, there is no clinical trials in targeting CAV1 in glioma cancer immunotherapy." (PMID 37642765, 2023). "Over-expression of CAV-1 induced the expression of p-PI3K, p-AKT, N-cadherin and Vimentin proteins in glioma cells, while decreasing E-cadherin proteins, without significant effects on the total levels of PI3K and AKT." (PMID 38298655, 2024). "Subsequent downregulation of CAV-1 decreased the levels of p-PI3K, p-AKT, N-cadherin, and Vimentin proteins in glioma cells, while increasing E-cadherin proteins, without significant effects on the total levels of PI3K and AKT." (PMID 38298655, 2024). "The AUC of CAV1 was 0.822 for LGG, 0.855 for GBMLGG, and 0.963 for GBM, suggesting that CAV1 could serve as a biomarker to distinguish glioma from non-tumor tissue." (PMID 37642765, 2023). "However, while these genes have been described to be expressed in glioma, we found the transcriptional levels of WNT6 are not significantly correlated with CAV1 (r = −0.03, P = 0.66) or PLAGL2 (r = 0.07, P = 0.36) in human GBM, and UCA1 and WNT6 are inversely correlated (r = −0.29, P < 0.001)." (PMID 31923345, 2020).
breast tumor (30 papers, 2004 to 2024). "Following this scenario, breast tumors with CEMM/CAV1 deficiency utilize autophagy as a pro-survival mechanism responding to Doxo treatment." (PMID 34786475, 2021). "Together, these studies indicate that the loss of cav-1 is an important driver of breast tumor progression." (PMID 28187162, 2017). "Of interest is the examination of whether the degree of stromal cav-1 loss coincides with increased fibronectin expression in breast tumors." (PMID 28187162, 2017). "Although tenascin-C appears to have a prominent role in breast tumor invasion and metastasis, we sought to determine whether the loss of cav-1 promoted increased mammary gland expression of tenascin-C." (PMID 28187162, 2017). "In addition, the loss of stromal cav-1 has also been reported to be a prognostic indicator for early breast tumor recurrence." (PMID 28187162, 2017). "One factor, which may drive ongoing matrix synthesis in breast tumors, is the loss of stromal caveolin-1 (cav-1), a scaffolding protein of caveolae, which has been linked to breast tumor aggressiveness." (PMID 28187162, 2017). "For instance, in breast tumors, CAV1 appears to shield tumor cells from cell death, promotes their survival, and prevents the activation of certain tumor-suppressing mechanisms." (PMID 39596307, 2024). "We then used an orthotopic breast tumor model to investigate the role of Ago2/CAV1 interaction in tumor formation and metastasis." (PMID 38649663, 2024). "Further, corresponding to the increased Ago2/CAV1 interaction in metastatic breast tumors, we observed that the levels of EV miR-3613-3p in circulation increase with tumor progression into metastasis." (PMID 38649663, 2024). "The mRNAs for EHD2 and Caveolin-1/2, structural components of caveolae, show co-overexpression across breast tumors, predicting shorter survival in basal-like BC." (PMID 36625722, 2023). "The female MMTV-Wnt1/Cav-1+/− mice developed more breast tumors (1.47 tumors vs. 1.14 tumors, P < 0.05) at an earlier age (19.6 weeks vs. 24.5 weeks, P < 0.05) compared with that of parental MMTV-Wnt1 mice." (PMID 32528105, 2020). "Three commonly predicted targets of the miR-17/92 cluster showing anti-correlated expression are tumor suppressors TGFBR2, DCN, and CAV1 which were under-expressed in the breast tumor tissues." (PMID 27213017, 2016). "The CAV1 gene has been shown by us and others to regulate breast tumor growth and metastasis and is overexpressed in basal-like subtypes." (PMID 23887935, 2013). "More specifically, high expression of CAV1 and CAV2 in stromal cells of breast tumors is associated with a more favorable prognosis, which is in line with their high expression in our good prognosis cluster." (PMID 20017941, 2009). "Mice models of orthotopic breast tumors were constructed and modified by injecting exosomes and exosomes with increased Cav-1 through tail veins to educate the lung microenvironment and form a PMN, meanwhile the PBS and exosome inhibitors were injected in control and compared groups, respectively." (PMID 37056561, 2023). "•Breast tumor CAV1 levels were assessed in relation to phenotype and prognosis." (PMID 35660849, 2022). "In addition, LSS protects breast tumor cells from anoikis under anchorage‐ independent conditions via a Cav‐1‐ dependent signaling pathway, by inhibiting Cav‐1‐dependent extrinsic and intrinsic apoptotic crosstalk signaling." (PMID 35992829, 2022). "In contrast to breast tumors associated with BRCA1, lack of caveolin-1 expression in breast tumors has been reported in patients with germline mutations in BRCA2, suggesting that the expression of caveolin-1 occurs only in tumors with mutations in BRCA1." (PMID 31244284, 2019). "Together, these reports suggest that abnormal matrix protein expression in breast tumors drives disease progression and that caveolin-1 may be an important regulator of matrix protein expression." (PMID 28187162, 2017).
breast tumor (continued). "There have been some studies investigating Cav-1 levels in breast tumor cells." (PMID 22356861, 2012). "Cav-1 may be useful with other markers in identifying/distinguishing claudin-low human breast tumors." (PMID 22356861, 2012). "There is preclinical and clinical evidence that caveolin-1 is a breast tumor suppressor gene." (PMID 17764562, 2007). "In cav-1 -/- glands, collagen fibers were not only more abundant but also appeared linearized, a finding which has previously been found to increase matrix stiffness and sequestration of tumor-promoting cytokines in addition to supporting breast tumor progression." (PMID 28187162, 2017). "However, we found high expression of Caveolin-1 in fibroblasts from both breast tumor specimens and disease-free tissues, indicating that, similar to αSMA, this protein could not distinguish between these cell types in vitro." (PMID 21957456, 2011). "In addition, in syngeneic mouse breast tumor models and xenotransplantation models, KDM5B knockout leads to upregulation of tumor suppressor genes such as BRCA1, CAV1, and HOXA5 and increased H3K4 methylation in the chromatin regions of these target genes." (PMID 35493099, 2022). "In breast tumor, caveolin-1-negative CAFs were proved to provides a fertile soil for tumor cell growth." (PMID 27901488, 2017). "Somewhat controversially, although the nSMase2-ceramide pathway is required for caveolin-1-mediated exosomes generation in mouse embryonic fibroblasts and MDA-MB468 breast tumor cells, inhibition or depletion of nSMase2 does not affect exosomal secretion of caveolin-1 in PC-3 cells." (PMID 36320056, 2022). "Thus, tumor promoting ability of fibroblasts did not depend on their tissue source of origin (i.e. breast tumor or reduction mammoplasty), nor did it associate with their extent of αSMA, FSP, FAP, or Caveolin-1 expression." (PMID 21957456, 2011). "Metastatic breast tumor cell lines show increased cell surface gp78/AMFR expression, however AMF/PGI uptake was increased only in metastatic MDA-435 cells that express gp78/AMFR and reduced Cav1 levels and not in MDA-231 cells expressing both gp78/AMFR and high levels of Cav1." (PMID 18974847, 2008).
Hyperglycemia (29 papers, 2013 to 2025). An increased concentration of glucose in the blood. "For diabetic kidney disease, OPCs can attenuate hyperglycemia-induced adverse cellular factors, such as cellular inflammation, and reduces genetic abnormalities caused by hyperglycemia, for example, caveolin-1." (PMID 37237870, 2023). "Significant hyperglycemia associated with enhanced gluconeogenesis and elevated lipolysis in CAV1 KO mice has been reported." (PMID 32718046, 2020). "High glucose regulates tau hyperphosphorylation and neuronal apoptosis through the TLR9-P38MAPK signalling pathway, and the hyperphosphorylation of tau protein and sustained hyperactivation of mTOR signalling in hyperglycaemia may be associated with the inhibition of caveolin-1 (Cav-1)." (PMID 38930877, 2024). "Post-stroke hyperglycemia during early reperfusion exacerbates BBB disruption by amplifying the Cav-1/autophagy axis." (PMID 41030451, 2025). "The GSK3 kinase has also been reported to be activated by hyperglycemia through the decrease in Caveolin-1 (Cav-1), which activates mTOR/SK6 pathway to activate GSK3, thereby increasing tau phosphorylation." (PMID 37638180, 2023). "CAV1, the coat proteins of caveolae, is indispensable for caveolae formation, which has been proven to facilitate the profibrotic response to hyperglycemia in DKD and participates in the transcytosis of glomerular endothelial cells." (PMID 35468852, 2022). "In our previous study, we demonstrated that hyperglycemia suppressed autophagic degradation of caveolin-1, which in turn resulted in acceleration of caveolae-mediated LDL transcytosis across endothelial cells and lipid retention." (PMID 32685103, 2020). "Chronic hyperglycemia decreases CAV1 expression in Schwann cells (SC), while antisense downregulation of CAV1 in SC increased neuregulin-induced demyelination in hyperglycemic conditions (HGC)." (PMID 32082483, 2020). "Taken together, these results identify caveolin-1 as a critical modulator of the pro-invasive phenotype induced by fulvestrant during hyperglycaemia-induced, matrix-specific EMT." (PMID 29331414, 2018). "Our mechanistic studies identified caveolin-1 as the major driver of the pro-invasive phenotype triggered by targeting FASN or the ERα during hyperglycaemia-induced, matrix-specific EMT." (PMID 29331414, 2018). "Our results suggest that tau hyperphosphorylation and the sustained over-activated mTOR signalling under hyperglycemia may be due to the suppression of Cav-1." (PMID 28489581, 2017). "Taken together, it suggests that the decline of cognitive function in DM is triggered by hyperglycemia, the process of cognitive dysfunction is contributed by suppressed Cav-1 expression, over-activated mTOR/S6K signalling, and/or the formation of tau hyperphosphorylation." (PMID 28489581, 2017). "Moreover, during hyperglycemia, Pin1 has been shown to interact with eNOS at Ser116 phosphorylation site, thereby promoting eNOS interaction with caveolin-1, an important repressor of eNOS catalytic activity in the endothelium and subsequently reducing NO availability." (PMID 34943794, 2021). "However, it should be noted that hyperglycemia in cav-1-deficient mice has not been reported in all cases." (PMID 31534971, 2019). "A study showed that hyperglycemia promotes albumin penetrance by upregulating the ROS/Src/Cav-1 pathway and downregulating the AMPK/Cav-1 pathway." (PMID 38259279, 2023). "Mice lacking caveolin 1 have multiple phenotypes including hyperglycaemia, lipidosis, and changes in endothelial permeability –, and humans with a loss of function mutation in caveolin 1 are severely lipodystrophic." (PMID 24013648, 2013). "Therefore, in contradiction with the results of the in vitro experiments, the in vivo experiments confirmed that hyperglycemia did not affect the expression of p-JAK2, p-STAT3, CAV-1, and p-NR2B." (PMID 30830585, 2019).
Hyperglycemia (continued). "In this study we have mimicked a major biochemical change observed in DM patients: chronic hyperglycemia, in primary hippocampal neurons and STZ-induced diabetic rat model, and have investigated whether or not Cav-1 is involved in the formation of tau hyperphosphorylation in HGC." (PMID 28489581, 2017).